COL9A3 (collagen type IX alpha 3 chain)
Description:
Structural component of hyaline cartilage and vitreous of the eye.
Synonyms: IDD; MED; EDM3; FLJ90759; DJ885L7.4.1; STL6
Tractability: Antibody: its Gene Ontology location is reachable by antibodies, with high confidence; UniProt places it where antibodies can reach, with medium confidence; UniProt predicts a signal peptide or a membrane-spanning region.
Gene: Protein-coding gene on chromosome 20 (62,816,244 to 62,841,163, forward strand). Ensembl gene ENSG00000092758.
Subcellular location: Secreted, extracellular space, extracellular matrix
Subcellular location (Human Protein Atlas): Nucleoplasm; Intermediate filaments; Predicted to be secreted
Pathways (Reactome):
Extracellular matrix organization: Assembly of collagen fibrils and other multimeric structures; Collagen biosynthesis and modifying enzymes; Collagen chain trimerization; Collagen degradation; ECM proteoglycans; Integrin cell surface interactions
Developmental Biology: NCAM1 interactions
Signal Transduction: Signaling by PDGF
Gene Ontology:
Molecular function: protein homodimerization activity; extracellular matrix structural constituent conferring tensile strength
Biological process: extracellular matrix organization
Cellular component: collagen type IX trimer; extracellular matrix; basement membrane; endoplasmic reticulum lumen; extracellular region
Genetic constraint (gnomAD): Loss-of-function variants: 87 observed, 101.35 expected, observed/expected ratio (o/e) 0.86, 90% interval 0.72 to 1.03. The synonymous counts are far from expectation, so gnomAD's model fits this gene poorly and the ratio says little. Missense variants: 1,042 observed, 907.14 expected, observed/expected ratio (o/e) 1.15, 90% interval 1.09 to 1.21. Synonymous variants: 487 observed, 378.13 expected, observed/expected ratio (o/e) 1.29, 90% interval 1.2 to 1.39.
Gene-disease validity (ClinGen):
ClinGen rates the evidence that COL9A3 causes each of these diseases.
Stickler syndrome (autosomal recessive): Definitive. Stickler syndrome is an inherited vitreoretinopathy characterized by the association of ocular signs with more or less complete forms of Pierre-Robin sequence, bone disorders, and sensorineural deafness (10% of cases).
Homologues: Orthologues: pig COL9A3 (90% identical). Paralogues in human: COL11A1 (45% identical), COL2A1 (44% identical), COL5A1 (44% identical), COL11A2 (44% identical), COL1A1 (44% identical), COL4A2 (43% identical), COL3A1 (43% identical), COL5A2 (43% identical), COL4A4 (43% identical), COL4A5 (42% identical), COL5A3 (42% identical), COL1A2 (41% identical), and 25 more.
Diseases named in the same sentence as COL9A3 in open-access papers:
COL9A3 is named in the same sentence as 63 diseases in open-access papers, as found by Europe PMC text mining. Sharing a sentence is not in itself a finding about the gene and the disease. The quoted sentences say what the papers report.
Stickler syndrome (14 papers, 2017 to 2025). "As a notable result, we also identified one case of phenotypically mild Stickler syndrome with a homozygous COL9A3 frameshift variant." (PMID 34824372, 2022). "Later, however, as the COL9A3 mutation was identified by genetic analysis, a detailed anamnestic re-evaluation of the associated symptoms of Stickler syndrome revealed a history of cataract and retinal detachment." (PMID 34824372, 2022). "Homozygous Type IX collagen variants (COL9A1, COL9A2, and COL9A3) causing recessive Stickler syndrome." (PMID 35198553, 2022). "The other case presented with Stickler syndrome with a mild phenotype caused by a homozygous frameshift COL9A3 variant." (PMID 34824372, 2022). "More rare than the AD forms, biallelic pathogenic variants in COL9A1, COL9A2, and COL9A3 have been reported to cause recessive forms of Stickler Syndrome (Stickler Syndromes 4-6 [STL4-6])." (PMID 32867104, 2020). "To date, multiple mutations in the collagen-encoding genes COL2A1, COL11A1, COL11A2, COL9A1, COL9A2, and COL9A3 have been associated with six genetically distinct types of Stickler syndrome." (PMID 28335520, 2017). "The COL9A3 gene, first reported as a genetic cause of multiple epiphyseal dysplasia, an autosomal dominant osteo-chondro-dysplasia, was also shown to be responsible for Stickler syndrome in two previous reports." (PMID 34824372, 2022). "Indeed, mutations in COL2A1, COL11A1, COL11A2, COL9A1, COL9A2, and COL9A3 have been associated with Stickler syndrome and early-onset OA." (PMID 28335520, 2017). "By contrast, Stickler syndrome has the most collagens (six) linked to this syndrome (COL2A1, COL9A1, COL9A2, COL9A3, COL11A1, and COL11A2), followed by Ullrich congenital muscular dystrophy, with four collagens associated (COL6A1, COL6A2, COL6A3, and COL12A1)." (PMID 37189830, 2023). "COL9A3 (OMIM: #120270) encodes for the α3 chain of collagen XI and is associated with Stickler syndrome (MIM: #620022) with autosomal recessive inheritance." (PMID 37895187, 2023). "Mutations in COL9A1, COL9A2 and COL9A3 cause multiple epiphyseal dysplasia (MED), an autosomal dominant chondrodysplasia, Stickler syndrome." (PMID 34572492, 2021). "The known causative genes of Stickler syndrome are COL2A1, COL11A1, COL11A2, COL9A1, COL9A2, and COL9A3." (PMID 34680973, 2021). "Since Stickler syndrome caused by COL9A1, COL9A2, and COL9A3 variants is very rare, most of the patients with Stickler syndrome are STL1 or STL2 patients if they have ocular abnormalities." (PMID 34680973, 2021). "Stickler syndrome caused by COL2A1, COL11A1, and COL11A2 genes has a dominant inheritance, whereas COL9A1, COL9A2, and COL9A3 genes show a recessive inheritance." (PMID 34680973, 2021). "To date, mutations in seven genes (COL2A1, COL11A1, COL11A2, COL9A1, COL9A2, COL9A3, and LOXL3) have been reported to cause Stickler syndrome." (PMID 32756486, 2020). "Whilst 8-I exhibited severe arthropathy requiring a wheelchair, their relative with an identical variant of COL9A3 (8-II) had no joint problems other than mild scoliosis, highlighting the phenotypic heterogeneity of recessive Stickler Syndrome." (PMID 39406934, 2025). "Whilst these two subtypes make up the majority of cases of Stickler Syndrome, several studies have identified cases of recessive SS, associated with both homozygous and compound heterozygous inheritance most commonly those encoding Type IX collagen, namely COL9A1, COL9A2 and COL9A3." (PMID 39406934, 2025). "Type 4, 5 and 6 Stickler syndromes (STL4, STL5 and STL6) have been attributed to homozygous or compound heterozygous mutations in the type IX collagen genes COL9A1, COL9A2 and COL9A3, respectively." (PMID 36140739, 2022). "The fact that COL9A3 is also annotated as AR in Orphanet (ORPHA:250984, Stickler syndrome) is not taken into account in the current implementation of the omimPrioritiser option." (PMID 32340307, 2020).
multiple epiphyseal dysplasia (10 papers, 2009 to 2025). Multiple epiphyseal dysplasias (MED/EDMs) are characterized by epiphyseal anomalies causing joint pain early in life, recurrent osteochondritis and early arthrosis. "In humans, mutations in COL9A3 have been associated with two genetically and phenotypically heterogenous types of osteochondrodysplasia, multiple epiphyseal dysplasia (MED) and pseudoachondroplasia (PSACH)." (PMID 33382735, 2020). "Other recognized genes within the 20q13.33 region include collagen Type IX, alpha-3 (COL9A3), splice-site mutations of which have been reported in families with multiple epiphyseal dysplasia." (PMID 20805988, 2010). "Subjects 2 and 6 in this study have deletions that encompass COL9A3, but the lack of clinical features reminiscent of multiple epiphyseal dysplasia suggests deletion of COL9A3 does not cause the syndrome." (PMID 20805988, 2010). "The genes implicating BMD variation and multiple epiphyseal dysplasias (MED) like COL1A1, COL1A2, CO9A1, COL9A2 and COL9A3 were highly suggestive in humans." (PMID 19284518, 2009). "Multiple epiphyseal dysplasia (MED) may be caused by mutations of genes encoding collagen IX, namely COL9A1 (encoding α1 chain), COL9A2 (α2 chain), and COL9A3 (α3 chain), but such mutations are not the main cause of MED." (PMID 35883515, 2022).
gastric cancer (8 papers, 2021 to 2025). A primary or metastatic malignant neoplasm involving the stomach. "USP3 can accelerate gastric cancer metastasis by enhancing the COL9A3/COL6A5 stability via deubiquitination." (PMID 37980532, 2023). "Epithelial–mesenchymal transition (EMT), invasion and migration in gastric cancer is mediated by ubiquitin-specific protease 3, which interacts with and deubiquitinates/stabilizes COL9A3 and COL6A5." (PMID 36765749, 2023). "High expression levels of both ubiquitin-specific protease 3 and COL9A3, compared to those of only one or low expression levels, result in the worst outcomes for patients with gastric cancer." (PMID 36765749, 2023). "Moreover, COL9A3 promotes epithelial-to-mesenchymal transition, invasion, and migration in gastric cancer." (PMID 38188020, 2023). "USP3 regulates COL9A3/COL6A5 stabilisation to promote gastric cancer progression." (PMID 36766336, 2023). "Similarly, USP3 was reported to promote the gastric cancer progression and metastasis by deubiquitinating COL9A3 and COL6A5." (PMID 37322017, 2023). "The deubiquitination enzyme USP3, an essential mediator regulating oncogenic activity both in vitro and in vivo, can deubiquitinate COL9A3 and COL6A5 in gastric cancer cells." (PMID 39759114, 2025). "The elevated USP3 expression can affect the abundance of COL9A3 and COL6A5, thereby promoting tumor proliferation and migration of gastric cancer cells." (PMID 39759114, 2025).
hearing loss (6 papers, 2020 to 2025). "DMGs for which gene variants were identified in association with hearing loss were also identified, including COL9A3 and SLC7A8; CACHD1 was also identified in connection to hearing loss in mice." (PMID 41159936, 2025). "Allelic disorders resulting from COL9A3 variants include nonsyndromic hearing loss, MED, pseudoachondroplasia, cerebral palsy, and lumbar disc disease and severe peripheral vitreoretinal degeneration and retinal detachment." (PMID 35241111, 2022). "This research proposed new genes associated with hearing loss, such as COL9A3 and TMPRSS3, and highlighted the impact of both common and rare variants on the risk of hearing loss." (PMID 40971385, 2025). "While a variety of disorders have been described to result from heterozygous pathogenic variants in COL9A3, only four unrelated STL families and one family with nonsyndromic hearing loss have been reported to date carrying biallelic variants." (PMID 35241111, 2022).
breast cancer (4 papers, 2015 to 2021). A primary or metastatic malignant neoplasm involving the breast. "Of note, NDRG4 expression emerged in this study within a group of epigenetically silenced genes in breast cancer cells that were significantly associated with integrin pathways (e.g., ITGA5 and COL9A3)." (PMID 30963110, 2019). "A previous study reported that COL9A3 potentially contributes to the pathogenesis of canine mammary tumours." (PMID 31297036, 2019).
lumbar disc disease (4 papers, 2018 to 2024). "SNPs that result in tryptophan polymorphisms in collagen IX genes, such as Trp2 allele (p.Gln326Trp) in COL9A2 and Trp3 allele in COL9A3, have been linked to an increased risk of lumbar disc disease in different populations." (PMID 38166944, 2024). "Previous study has proven that the allelic variants in the collagen IX gene-COL9A3 was a genetic risk factor for intervertebral disc disease, and two single nucleotide polymorphisms introducing in COL9A3 were linked to an increased risk of lumbar disc disease." (PMID 33691689, 2021). "An increasing number of studies have investigated associations between collagen IX alpha 2 chain (COL9A2) and collagen IX alpha 3 chain (COL9A3) gene polymorphisms and the risk of lumbar disc degeneration (LDD)." (PMID 29506578, 2018). "For instance, the Trp3 allele in COL9A3 was found not clustered in lumbar disc degeneration, and the genotype of Trp3 allele was not related to clinical symptoms." (PMID 38166944, 2024).
osteoarthritis (4 papers, 2012 to 2024). A noninflammatory degenerative joint disease occurring chiefly in older persons, characterized by degeneration of the articular cartilage, hypertrophy of bone at the margins and changes in the synovial membrane. "Mutations in COL9A2 and COL9A3 have previously been linked to human disk disease and studies in transgenic mice have further demonstrated that mutations in collagen IX can lead to disk degeneration but also degenerative joint disease." (PMID 23125846, 2012).
autosomal recessive Stickler syndrome (3 papers, 2022). "Mutations in COL9A3 cause autosomal-recessive Stickler syndrome, a disorder affecting connective tissue (such as the spiral ligament) and commonly leading to hearing loss." (PMID 35580588, 2022).
deafness (3 papers, 2022 to 2023). An inherited or acquired condition characterized by the complete loss of the ability to hear from one or both ears. "Twenty-five genes were present in both male and female hearing difficulty high variant load lists, including seven deafness genes (CLIC5, MYH14, COL9A3, ELMO3, FSCN2, GJB2, SLC26A5)." (PMID 35761239, 2022).
intervertebral disc disease (3 papers, 2021 to 2024). "We summarized the phenotypes, sampling regions, sample sizes and statistical results of COL9A3 pathogenic variants in intervertebral disc diseases and found that results from different studies were inconsistent." (PMID 38166944, 2024). "Trp3 allele in COL9A3 gene has been widely studied in populations with intervertebral disc disease." (PMID 38166944, 2024). "In addition, a number of meta-analysis studies did not observe the association between the COL9A3 Trp3 polymorphism and disc degeneration." (PMID 38166944, 2024).
myopia (3 papers, 2020 to 2022). "Second, patients with COL9A1 and COL9A3 mutations mainly present with moderate to severe myopia and rarely with retinal detachment." (PMID 32756486, 2020). "Consistent clinical features among STL patients with biallelic COL9A3 LOF alleles comprise moderate-to-profound progressive sensorineural hearing loss and moderate high myopia with vitreoretinal degeneration." (PMID 35241111, 2022).
retinal detachment (3 papers, 2020 to 2022). An eye emergency condition which may lead to blindness if left untreated. "Very recently, heterozygous COL9A3 variants have been identified as causing peripheral vitreoretinal degeneration and retinal detachment." (PMID 35241111, 2022). "In the candidate gene approach, COL9A2, COL9A3, NHEJ1, RS1 and NDP genes were investigated based on their known associations with RD and retinal detachment in dogs and humans." (PMID 33945575, 2021).
chondrodysplasia (2 papers, 2018 to 2021). "Mutations in the COL9A3 gene could cause chondrodysplasias in humans as well as articular cartilage and IVDD in mice." (PMID 34572492, 2021). "Mutations in COL9A3 could cause chondrodysplasias in humans as well as articular cartilage and intervertebral discs degeneration in mice." (PMID 30342505, 2018).
osteosarcoma (2 papers, 2022 to 2024). A usually aggressive malignant bone-forming mesenchymal neoplasm, predominantly affecting adolescents and young adults. "Additionally, five key genes, including CD4, RUNX2, OMD, COL9A3, and JUN, were found to be associated with osteosarcoma progression." (PMID 39324133, 2024). "The expression of CD4, OMD, and JUN was decreased in Osteosarcoma cells compared with osteoblasts, whereas RUNX2 and COL9A3 expression was increased." (PMID 36686663, 2022).
triple-negative breast carcinoma (2 papers, 2021). An invasive breast carcinoma which is negative for expression of estrogen receptor (ER), progesterone receptor (PR), and human epidermal growth factor receptor 2 (HER2). "As for tumor-related research, COL9A3 was identified as tumor suppressor gene in rectal cancer, and it was also significantly associated with the prognosis of triple-negative breast cancer as an independent prognostic signature." (PMID 33691689, 2021). "COL9A3 might be correlated with the pathogenesis of triple-negative breast cancer, and the polymorphisms of COL6A5 might be relevant to lung cancer susceptibility among Chinese Han individuals." (PMID 34930901, 2021).
vitreoretinal degeneration (2 papers, 2019 to 2022). "Similarly, in OSD-affected NID, the variant in COL9A3 most likely disrupts the function of collagen IX, which presents clinically as vitreoretinopathy and skeletal dysplasia." (PMID 31415586, 2019).
clubfoot (1 paper, 2023). The most common congenital deformation of the foot, occurring in 1 of 1,000 live births. "Mutations in genes encoding the ECM proteins COL9A1, COL9A2, COL9A3, COMP and MATN3, as well as the transmembrane glycoprotein involved in matrix organization, SLC26A2, have been associated with clubfoot." (PMID 37964341, 2023).
depression (1 paper, 2025). "This study highlights the critical role of lncRNA Six3os1 in the pathological mechanisms of depression, demonstrating that it positively regulates COL9A3 by suppressing miR‐511‐3p, thereby modulating the MAPK/NLRP3 signaling axis." (PMID 41341504, 2025). "Additionally, this study is the first to report the potential protective role of COL9A3 in depression, identifying it as a promising therapeutic target." (PMID 41341504, 2025). "Six potential depression‐related target genes of miR‐511‐3p were identified: CXCR4, LBR, CPS1, VPS13B, COL9A3, and GABRB3." (PMID 41341504, 2025).
developmental delay (1 paper, 2014). "A study characterizing a microdeletion of 20q13.33, a cytogenetic locus in which COL9A3 is located, demonstrated that this abnormality is associated with several clinical features including mental retardation, developmental delay, speech and language deficits, behavior problems and seizures." (PMID 25381065, 2014).
dwarfism with (1 paper, 2019). "Variants associated with OSD have been identified in COL9A3 in the Labrador Retriever and in COL9A2 in the Samoyed dog, termed drd1 and drd2 (dwarfism with retinal dysplasia 1 and 2) respectively." (PMID 31415586, 2019). "Autosomal recessive OSD caused by COL9A3 and COL9A2 mutations have previously been identified in the Labrador Retriever (dwarfism with retinal dysplasia 1—drd1) and Samoyed dog (dwarfism with retinal dysplasia 2—drd2) respectively; both of those mutations were excluded in all affected NID." (PMID 31415586, 2019).
leukemia (1 paper, 2022). A malignant (clonal) hematologic disorder, involving hematopoietic stem cells and characterized by the presence of primitive or atypical myeloid or lymphoid cells in the bone marrow and the blood. "Finally, within CSF + LM group, differential protein profiles were observed between leukemia and lymphoma (such as FCGR1, CR2, ABL1, PTPRC, SELP, ITGB1, COL9A3 or ITGAX), which could subtype the CSF + LM depending on the primary tumor." (PMID 35053611, 2022).
lumbar disc herniation (1 paper, 2024). "We identified a novel pathogenic variant in COL9A3 gene in a pedigree with multiple lumbar disc herniation (LDH)." (PMID 38166944, 2024).
melanoma (1 paper, 2021). A malignant, usually aggressive tumor composed of atypical, neoplastic melanocytes. "COL9A3 encodes instructions for generating one of the three alpha chains of type IX collagen and is highly expressed in salivary adenoid cysts, breast basal-like carcinomas, and melanoma." (PMID 34855841, 2021).
meningioma (1 paper, 2022). A generally slow growing tumor attached to the dura mater. "We found that the expression of COL2A1, and COL9A3 were significantly upregulated in meningioma tissues, and the expression of COL14A1, COL4A3, and COL4A2 was significantly down-regulated." (PMID 36538194, 2022).
Obesity (1 paper, 2013). Accumulation of substantial excess body fat. "We cannot exclude gene-environmental factor interactions such as those shown for obesity and the COL9A3 gene." (PMID 23497297, 2013).